SLC39A6 (solute carrier family 39 member 6)
Description:
Zinc-influx transporter which plays a role in zinc homeostasis and in the induction of epithelial-to-mesenchymal transition (EMT). When associated with SLC39A10, the heterodimer formed by SLC39A10 and SLC39A6 mediates cellular zinc uptake to trigger cells to undergo epithelial- to-mesenchymal transition (EMT). The SLC39A10-SLC39A6 heterodimer also controls NCAM1 phosphorylation and its integration into focal adhesion complexes during EMT (By similarity). Zinc influx inactivates GSK3B, enabling unphosphorylated SNAI1 in the nucleus to down-regulate adherence genes such as CDH1, causing loss of cell adherence. In addition, the SLC39A10-SLC39A6 heterodimer plays an essential role in initiating mitosis by importing zinc into cells to initiate a pathway resulting in the onset of mitosis. Participates in the T-cell receptor signaling regulation by mediating cellular zinc uptake into activated lymphocytes. Regulates the zinc influx necessary for proper meiotic progression to metaphase II (MII) that allows the oocyte-to-egg transition.
Synonyms: LIV1; ZIP6; LIV-1
Tractability: Antibody: UniProt places it where antibodies can reach, with high confidence; its Gene Ontology location is reachable by antibodies, with high confidence; UniProt predicts a signal peptide or a membrane-spanning region. PROTAC: ubiquitination databases record sites on it; its protein half-life has been measured. Other modalities: a drug acting on it is in phase 2 or 3 trials.
Target class: SLC superfamily of solute carriers; Transporter; Electrochemical transporter; SLC39 family of metal ion transporters
Gene: Protein-coding gene on chromosome 18 (36,108,531 to 36,129,385, reverse strand). Ensembl gene ENSG00000141424.
Subcellular location: Cell membrane; Cell projection, lamellipodium membrane; Membrane raft; Apical cell membrane
Subcellular location (Human Protein Atlas): Cytosol; Nucleoplasm; Plasma membrane
Pathways (Reactome):
Transport of small molecules: Zinc influx into cells by the SLC39 gene family
Gene Ontology:
Molecular function: protein binding; zinc ion transmembrane transporter activity; monoatomic cation:bicarbonate symporter activity; metal ion transmembrane transporter activity
Biological process: epithelial to mesenchymal transition; intracellular zinc ion homeostasis; lymphocyte activation; T cell receptor signaling pathway; zinc ion import across plasma membrane; zinc ion transmembrane transport; intracellular monoatomic cation homeostasis; bicarbonate transport; metal ion transport; transmembrane transport
Cellular component: cell surface; lamellipodium membrane; membrane raft; plasma membrane; apical plasma membrane; endoplasmic reticulum; membrane
Genetic constraint (gnomAD): Loss-of-function variants: 35 observed, 47.54 expected, observed/expected ratio (o/e) 0.74, 90% interval 0.56 to 0.98. The upper end of that interval is the gene's LOEUF score, 0.98, which puts it in group 4 of 6, group 1 being the genes least tolerant of losing a copy. Missense variants: 699 observed, 818.2 expected, observed/expected ratio (o/e) 0.85, 90% interval 0.8 to 0.91. Synonymous variants: 276 observed, 291.11 expected, observed/expected ratio (o/e) 0.95, 90% interval 0.86 to 1.05.
Homologues: Orthologues: chimpanzee SLC39A6 (99% identical), macaque SLC39A6 (95% identical), dog SLC39A6 (91% identical), pig SLC39A6 (90% identical), rabbit SLC39A6 (89% identical), guinea pig SLC39A6 (88% identical), mouse Slc39a6 (87% identical), rat Slc39a6 (87% identical), zebrafish slc39a6 (44% identical), tropical clawed frog slc39a6 (23% identical), Caenorhabditis elegans zipt-15 (14% identical). Paralogues in human: SLC39A10 (36% identical), SLC39A5 (22% identical), SLC39A14 (20% identical), SLC39A4 (20% identical), SLC39A12 (19% identical), SLC39A8 (18% identical).
Diseases named in the same sentence as SLC39A6 in open-access papers:
SLC39A6 is named in the same sentence as 43 diseases in open-access papers, as found by Europe PMC text mining. Sharing a sentence is not in itself a finding about the gene and the disease. The quoted sentences say what the papers report.
breast cancer (60 papers, 2007 to 2025). A primary or metastatic malignant neoplasm involving the breast. "The expression and activity of one such transporter ZIP6 (SLC39A6), has long been associated with oestrogen receptor (ER)-positive breast cancer, being utilized in a clinical setting to identify luminal A breast cancer." (PMID 35591900, 2022). "In this study, nanobody against SLC39A6 protein was selected to be used as diagnostic and therapeutic tool in breast cancer which was prepared from an immune library." (PMID 35432806, 2021). "SLC39A6 (solute carrier family 39) or LIV-1, is a zinc-transporter protein associated with estrogen-positive breast cancer and its metastatic spread." (PMID 35432806, 2021). "SLC39A6 was linked to MET in breast cancer through SLC39A6-induced zinc influx when N-terminal cleavage inactivates GSK-3β; as a result, unphosphorylated Snail in the nucleus downregulates the adherence genes, such as E-cadherin." (PMID 26444413, 2015). "One subfamily of ZIP, estrogen-regulated LIV-1 (SLC39A6) has been implicated in breast cancer." (PMID 36421686, 2022). "Given that increased expression of SLC39A6 is implicated in lymph node involvement in breast cancer, it is suggested that it may play a role in metastasis." (PMID 35432806, 2021). "For example, overexpression of SLC39A6 can promote migration and invasion of breast cancer cells due to its regulation of multiple signaling pathways such as EMT (epithelial-mesenchymal transition) and cytoskeletal remodeling via zinc ions." (PMID 39228303, 2024). "LIV-1, or SLC39A6, is a zinc transporter protein that is expressed in BC, and it was first identified as an estrogen-inducible gene in cell lines established from breast cancer." (PMID 39456611, 2024). "The prognostic significance of SLC39A6 mRNA expression was examined in Bc-GenExMiner v4.0 (Breast Cancer Gene-Expression Miner v3.0), online data set available at http:// bcgenex.centregauducheau.fr." (PMID 34453638, 2021). "During two past decades, a lot of studies for the treatment of breast cancer was done; these studies have shown that the expression of SLC39A6 increased in ER (estrogen receptor) positive breast cancer patients." (PMID 35432806, 2021). "The high expression of SLC39A6 is a dependable marker for breast cancer (luminal A subtype), and elevated SLC39A10 mRNA levels were evident in the cancer cell lines of the highly aggressive breast cancer." (PMID 34925450, 2021). "The C3 Nanobody was capable of detecting SLC39A6 at the surface of cells, it possesses that can be used as a marker of SLC39A6 breast cancer." (PMID 35432806, 2021). "Based on the results of the affinity test C3 nanobody has The C3 Nanobody was capable of detecting SLC39A6 at the surface of cells, it possesses that can be used as a marker of SLC39A6 breast cancer." (PMID 35432806, 2021). "SLC39A6 plays a critical role in maintaining zinc homeostasis, and was originally identified as an estrogen-induced gene in a breast cancer cell line." (PMID 26444413, 2015). "SLC39A6 is modified via N-terminal cleavage before this protein relocates to the plasma membrane in breast cancer." (PMID 26444413, 2015). "Increased expression of these genes also correlated with a decreased risk of breast cancer recurrence, although only four (RABEP1, PGR, SLC39A6 and FUT8) exhibited significant adjusted p-values." (PMID 23819905, 2013). "However, in luminal breast cancer, the Oestrogen-regulated protein SLC39A6 acts as a benign prognostic indicator." (PMID 36341437, 2022). "Our findings were consistent with those of the previous study, in that high mRNA expression levels of SLC39A6 and SLC39A14 indicated favorable OS, but upregulated SLC39A2-5, SLC39A7, and SLC39A12-13 were associated with poor OS in the patients with breast carcinoma." (PMID 34925450, 2021).
breast cancer (continued). "Because the zinc LIV-1(SLC39A6) transporter is expressed in all breast cancer subtypes, Seattle Genetics constructed a novel antibody-drug conjugate, SGN-LIV1A, targeting LIV-1 for the treatment of metastatic breast cancer." (PMID 32944394, 2020). "Multivariable analyses using the LASSO revealed that expression of PGR, ESR1, NAT1, GABRP, TBC1D9, SLC39A6 and LRBA of the 32 gene candidates was collectively the most important predictors for both breast cancer mortality and recurrence." (PMID 23819905, 2013). "SLC39A6 has been reported to regulate SNAIL and E-cadherin expression in breast cancer." (PMID 26684241, 2016). "Utilizing the characteristics of the zinc SLC39A6 transporter widely expressed in all breast cancer subtypes, Seattle Genetics has designed and constructed a new antibody–drug conjugate called SGN-LIV1A to treat metastatic breast cancer through the targeted regulation of SLC39A6." (PMID 34925450, 2021).
prostate carcinoma (9 papers, 2011 to 2025). A carcinoma that arises from epithelial cells of the prostate gland. "SLC39A6, also named LIV-1, is a zinc transporter that regulates the invasion and metastasis of pancreas, breast and prostate cancers." (PMID 26684241, 2016). "SLC39A6 regulates the invasion and metastasis of pancreas, esophageal and prostate cancers." (PMID 29435142, 2018). "SLC39A6 has been shown to regulate the invasion and metastasis of breast and prostate cancers." (PMID 26684241, 2016). "SLC39A6, also named LIV-1, is a zinc transporter that regulates the invasion and metastasis of pancreas, esophageal and prostate cancers." (PMID 29435142, 2018).
breast tumors (6 papers, 2012 to 2025). "SLC39A6 expression has been described in clinical breast-tumour populations as significantly associated with the estrogen receptor status." (PMID 26992213, 2016). "Statistical analysis of Zn transporter expression indicated that similar to what was observed in breast tumor tissues, basal-like cancer cells also had significantly higher expression of MTs and SLC39A14 and lower expression of SLC39A6, SLC39A9, and SLC39A11 (fold-change >1.5; FDR, p < 0.05)." (PMID 26728511, 2016).
cervical cancer (5 papers, 2011 to 2021). A primary or metastatic malignant neoplasm involving the cervix. "Overexpression of SLC39A6 increased cell proliferation and regulated metastasis in esophageal and cervical cancer cells while knockdown of SLC39A6 suppressed cell proliferation and reduced lymphatic metastasis." (PMID 33007803, 2020).
esophageal cancer (5 papers, 2014 to 2022). A primary or metastatic malignant neoplasm involving the esophagus. "Another example is that we found a genetic variant in the 5′UTR of SLC39A6 associated with shorter survival in esophageal cancer, which may be attributed to alleviating SLC39A6 repression and promoting cancer cell invasion and metastasis." (PMID 32737864, 2021). "In studies of esophageal cancer, SLC39A6 increases the invasiveness of esophageal cancer cells and reduces patient prognosis by increasing the level of Zinc expression in esophageal cancer cells." (PMID 36341437, 2022). "To ascertain that SLC39A6 is essential for esophageal cancer cell proliferation, we used siRNAs to deplete SLC39A6 protein in ESCC cells." (PMID 26444413, 2015). "SLC39A6 can also be used as an indicator for early diagnosis of esophageal cancer." (PMID 36341437, 2022). "Therefore, more studies are necessary to characterize the expression of SLC39A6 during the multi-stage development of esophageal cancer, and determine its prognostic value." (PMID 26444413, 2015). "However, whether SLC39A6 is activated via N-terminal cleavage in esophageal cancer should be clarified in future studies." (PMID 26444413, 2015). "And the effects of SLC39A6 silencing by siRNA on cell proliferation, apoptosis, and invasiveness, as well as the proteins involved in epithelial-to-mesenchymal transition (EMT) of esophageal cancer cells, were studied." (PMID 26444413, 2015). "Although only one large-scale GWAS reported SLC39A6 as the susceptibility gene of ESCC and the expression level in a Chinese Han population, no other report has discussed the expression of SLC39A6 in precursor lesions and other ethnic patients with esophageal carcinoma." (PMID 26444413, 2015).
triple-negative breast carcinoma (5 papers, 2021 to 2025). An invasive breast carcinoma which is negative for expression of estrogen receptor (ER), progesterone receptor (PR), and human epidermal growth factor receptor 2 (HER2). "Expression of SLC39A6 is a strong prognostic indicator in breast cancer, with high levels associated with a good prognosis in luminal subtypes, but predicting poor survival and failure to respond to treatment in triple negative breast cancer." (PMID 41583444, 2025). "Of these interesting genes, SLC39A6 is identified as a therapeutic target in previous reports for Ladiratuzumab Vedotin (a Zinc transporter ZIP6 binding agent) drug to treat triple-negative breast cancer and angiosarcoma." (PMID 37641095, 2023). "Ladiratuzumab vedotin, an antibody–drug conjugate that targets SLC39A6/LIV-1, is currently undergoing clinical research as a treatment for metastatic and triple-negative breast cancer." (PMID 39218897, 2024). "According to Seattle Genetics, the LIV-1 (SLC39A6) expression level was maintained after hormone therapy at both primary and metastatic sites; however, it was elevated in patients with triple-negative breast cancer." (PMID 37049543, 2023).
hepatocellular carcinoma (4 papers, 2013 to 2025). A malignant tumor that arises from hepatocytes. "Additionally, miR-192 targets TRIM25 to inhibit proliferation and migration in hepatitis B virus-related hepatocellular carcinoma, and targets SLC39A6 to reduce tumor metastasis in hepatocellular carcinoma cells." (PMID 40087755, 2025).
pancreatic cancer (4 papers, 2011 to 2021). "Moreover, downregulation of SLC39A6 inhibits pancreatic cancer cell proliferation in vitro and reduces tumor growth and metastasis in vivo, which indicates the aggressive role of SLC39A6 in pancreatic cancer." (PMID 33783998, 2021).
liver cancer (3 papers, 2013 to 2022). An epithelial or non-epithelial malignant neoplasm that arises from the liver. "Previous studies have shown that SLC39A6 is overexpressed in breast, prostate, pancreatic, cervical, and liver cancers." (PMID 26444413, 2015). "Generally, elevated SLC39A6 expression is reportedly related to cancer progression in other various types of cancer, including breast, prostate, pancreatic, cervical and liver cancers." (PMID 26444413, 2015).
lung carcinoma (3 papers, 2018 to 2023). "The results indicated that miR-101-3p and SLC39A6 might be useful prognostic markers for lung cancer patients at all disease stages." (PMID 29435142, 2018).
neuroblastoma (3 papers, 2015 to 2022). Neuroblastoma (NB) is the most common solid, extracranial childhood tumor. "SLC39A6 is shown to mediate the incorporation of extracellular Zn2+ in SH-SY5Y neuroblastoma cells, however, whereas SLC39A7 regulates mobilization of Zn2+ from Golgi apparatus to the cytoplasm." (PMID 26010609, 2015).
gastric cancer (2 papers, 2019 to 2023). A primary or metastatic malignant neoplasm involving the stomach. "Although several polymorphisms have been linked to gastric cancer, we focused on polymorphism in the SLC39A6 (LIV-1) gene because it is a downstream target of the STAT3 oncoprotein and promotes cancer progression by increasing cell growth and differentiation." (PMID 31703635, 2019). "The potential involvement of SLC39A6 in gastric cancer was explored in clinical samples and cell culture studies." (PMID 31703635, 2019).
intraepithelial neoplasia (1 paper, 2015). A precancerous neoplastic process that affects the squamous, glandular, or transitional cell epithelium without evidence of invasion. "SLC39A6 protein expression increased progressively from normal esophageal epithelium (NEE) to low-grade intraepithelial neoplasia to ESCC, and finally reached the highest in high-grade intraepithelial neoplasia from Han ethnic." (PMID 26444413, 2015).
prostate adenocarcinoma (1 paper, 2025). "The volcano plot indicated significant upregulation of genes such as SIM2, HPN, and HOXC6 in prostate adenocarcinoma (PRAD), and significant downregulation of genes such as SLC39A2, SLC39A6, and SLC39A10." (PMID 40978029, 2025).
vascular tumor (1 paper, 2016). "SLC39A6 was upregulated in HCC samples and positively correlated with vascular tumor cell invasion and pathological stage." (PMID 26684241, 2016).